SCNN1B (sodium channel epithelial 1 subunit beta)
Diseases named in the same sentence as SCNN1B in open-access papers (continued):
Sharing a sentence is not in itself a finding about the gene and the disease.
emphysema (4 papers, 2019 to 2025). "Altogether, these findings suggest that Scnn1b-Tg mice have underlying emphysema like many pwCF, and inoculation of Scnn1b-Tg mice with sterile agar beads does not change these properties relative to WT C57BL/6 mice littermates." (PMID 40512037, 2025). "The genetic deletion of Il1r1, a gene encoding the receptor for IL-1α and IL-1β, abolishes airway neutrophilia and significantly reduces mortality, mucoobstruction, and emphysema in Scnn1b-Tg+ pups." (PMID 31396541, 2019). "Matrix metalloproteinase- (MMP-) 12, a candidate genetic contributor to the development of emphysema, was found to be upregulated in the lungs of Scnn1b-Tg+ mice." (PMID 31396541, 2019). "MMP12 is critical in the formation of emphysema in Scnn1b-Tg+ model." (PMID 40496925, 2025). "Kcnn4 silencing in the Scnn1b-transgenic mouse (Scnn1btg/+), a model of muco-obstructive lung disease triggered by increased epithelial Na+ absorption, improved MCC, reduced Na+ absorption, and did not change the amount of mucus but did reduce mucus adhesion, neutrophil infiltration, and emphysema." (PMID 32814712, 2020).
asthma (3 papers, 2014 to 2024). "Interestingly, a few genes such as NRM, PTPRE and SUZ12 were observed to be associated with Rheumatoid Arthritis, Asthma and Endometrial Stromal Sarcoma diseases, respectively, in humans and genes like SCNN1B associated with renal disease in cattle." (PMID 38674383, 2024). "The asthma model used displays a Th2 phenotype, while the adult Scnn1b-Tg mice used in this study rather displays a Th1 phenotype." (PMID 25027175, 2014). "Both M1 and M2 signature genes were markedly upregulated in Scnn1b-Tg AMs, and genes related to muco-obstructive lung diseases such as CF, COPD, and asthma, were positively enriched in Scnn1b-Tg AMs." (PMID 34764283, 2021).
chronic obstructive lung disease (3 papers, 2013 to 2021). "We, therefore, used Scnn1b-transgenic (Tg) mice as a model of chronic obstructive pulmonary disease (COPD) and compared uptake and localization of inhaled AuNP in surface macrophages and lung tissue to wild-type (Wt) mice." (PMID 23680060, 2013). "Hence, the results from lung tissue analysis provide evidence for a prolonged residence time of AuNP on the lung surface in chronic obstructive lung disease in Scnn1b-Tg mice resulting in increased NP uptake by epithelial cells." (PMID 23680060, 2013).
obstructive lung disease (3 papers, 2014 to 2025). "Taken together, the lung mechanics confirmed an initial obstructive lung disease in Scnn1b-Tg mice and demonstrated the establishment of a mixed obstructive/restrictive pathology during chronic infection in the SCFM2-Scnn1b-Tg mice." (PMID 40512037, 2025).
clear cell kidney carcinoma (2 papers, 2017 to 2020). "Another candidate, SCNN1B, a part of a multiprotein complex consisting of three subunits that control fluid and electrolyte transport across epithelia in diverse organs, has been shown to be silenced by promoter methylation in GC and clear cell renal cell cancer." (PMID 31959204, 2020).
glioma (2 papers, 2023 to 2024). A benign or malignant brain and spinal cord tumor that arises from glial cells (astrocytes, oligodendrocytes, ependymal cells). "Other mitochondrial genes such as ABCC3, HOXA4, HOXC10, NNMT, and SCNN1B are typically increased in their expression as the grade of glioma and the higher expression of these genes have been associated with poor prognosis in LGG." (PMID 39012280, 2024). "The results of in vitro experiments showed that high SCNN1B expression promoted the migration of glioma cells." (PMID 37334354, 2023). "To further determine the biological function of SCNN1B, we utilized siRNAs to knockdown SCNN1B in SNB-19 glioma cell line." (PMID 37334354, 2023). "The functional experiments showed a significant decrease in the migration of glioma after knockdown of SCNN1B." (PMID 37334354, 2023). "Additionally, the transwell assay revealed a consistent decrease in migration ability in SNB-19 cells after SCNN1B knockdown (#1, P<0.001; #2, P<0.001), indicating the crucial role of SCNN1B in gliomas." (PMID 37334354, 2023).
hyperkalaemia (2 papers, 2022 to 2024). "However, we noted that increased level of SCNN1B expression was associated with numerically lower and nominally significant risk for hyperkalaemia in UK Biobank consistent with the lowering effect of upregulated ENaCs on circulating levels of potassium." (PMID 38504097, 2024). "Our results have confirmed the associations of mutations in the SCNN1B gene with recurrent hyperkalaemia, which can cause severe PHA type I disease, meanwhile suggested clinical attention should be paid when persistent recurrent hyperkalemia is accompanied by these types of mutations." (PMID 35359893, 2022).
adenoma (1 paper, 2024). A neoplasm arising from the epithelium. "Finally, we did not evaluate the methylation levels and expression of SCNN1B in the control group with benign colorectal polyps or adenomas." (PMID 39415304, 2024).
allergic asthma (1 paper, 2014). A asthma with a basis in a pathological type I hypersensitivity reaction. "Bronchoalveolar lavage (BAL) cells from diseased mice (allergic asthma: ovalbumin [OVA] sensitized and COPD: Scnn1b-transgenic [Tg]) and their respective healthy controls were exposed ex vivo first to 3-μm fungal spores of Calvatia excipuliformis and then to 20-nm gold (Au) NP." (PMID 25027175, 2014).
breast carcinoma (1 paper, 2024). "Based on our extensive search, it also identified several new potential genes associated with breast cancer progression, including HPCA, SLC9A2, SCNN1B, SULT4A1, and GUCY2D." (PMID 39768011, 2024).
chronic bronchitis (1 paper, 2019). A type of chronic obstructive pulmonary disease characterized by chronic inflammation in the bronchial tree that results in edema, mucus production, obstruction, and reduced airflow to and from the lung alveoli. "Male and female wildtype (WT) and Scnn1b-transgenic (βENaC) mice, which have chronic bronchitis and emphysematous changes due to dehydrated mucus, were exposed to cigarette smoke or sham air conditions for 1 or 5 days." (PMID 30818335, 2019).
gastrointestinal stromal tumor (1 paper, 2022). "Furthermore, the results revealed that two of the four central DEGs (ATP1A2, PLN, KCNMA1, and SCNN1B) of the PPI network were created in this module, thus suggesting that PLN and ATP1A1 may have a significant important role in gastrointestinal stromal tumors." (PMID 35655923, 2022).
lymph node metastasis (1 paper, 2024). "However, the high methylation levels of fragment one in the SCNN1B promoter showed a significant association with advanced tumour stage (P = 0.004) and lymph node metastasis (P = 0.003) in CRC patients." (PMID 39415304, 2024). "The correlation between the methylation levels of SCNN1B and the clinicopathological parameters of the CRC patients, such as age, sex, tumour differentiation, tumour stage, lymph node metastasis, tumour localization, RAS mutation, BRAF mutation, and MSI status, was evaluated." (PMID 39415304, 2024).
pseudohypoaldosteronism (1 paper, 2021). An inherited or acquired disorder of electrolyte metabolism, characterized by the inability of the renal tubules to respond to aldosterone. "It has been shown in murine models and among patients that the expression levels of SCNN1B need to be tightly controlled to prevent pathological conditions: Reduced expression of Scnn1b in mice causes pseudohypoaldosteronism." (PMID 34680949, 2021). "SCNN1B is known to cause Liddle syndrome (OMIM #177200), pseudohypoaldosteronism (OMIM #264350), and to contribute to the manifestation of bronchiectasis (OMIM #211400) and CF-like disease." (PMID 34680949, 2021).
retinoblastoma (1 paper, 2024). A malignant tumor that originates in the nuclear layer of the retina. "In the case of cattle, genes like TRPA1, RB1 and SCNN1B are predicted to be involved in respiratory diseases, retinoblastoma and renal diseases, respectively." (PMID 38674383, 2024).
tumor (13 papers, 2009 to 2025). "Our results showed that elevated SCNN1B methylation levels in CRC tissues were significantly related to advanced tumour stage and a high risk of lymph node metastasis." (PMID 39415304, 2024). "Analogously, SCN9A and SCNN1B down-regulation was highly associated with tumor epithelial cell-enriched fractions." (PMID 33802791, 2021). "Furthermore, high methylation levels of the SCNN1B promoter were correlated with advanced tumour stage, an increased risk of lymph node metastasis and poor prognosis in CRC patients." (PMID 39415304, 2024). "In addition, the high methylation levels and low mRNA expression of SCNN1B showed a significant association with advanced tumour stage, increased risk of lymph node metastasis and poor prognosis of CRC patients." (PMID 39415304, 2024). "The effect of SCNN1B on cytokinetics, therefore, underlies its tumor suppressive function in CRC." (PMID 36564468, 2023). "The anti-tumor effect of SCNN1B is mediated via degradation of the endoplasmic reticulum chaperone GRP78, which is frequently up-regulated during cancer progression to counter unfolded protein response (UPR), maintain ER homeostasis and promote cell survival." (PMID 39415304, 2024). "SCNN1B can inhibit tumor cell proliferation and colony formation by inhibiting c‐Raf, and further inhibit carcinogenic MEK–ERK signaling, thus playing a tumor suppressor role." (PMID 39711442, 2024). "The results showed that SCNN1B was significantly hypermethylated in tumour tissues of CRC patients compared to their adjacent normal tissues." (PMID 39415304, 2024). "The significant association between methylation and mRNA levels of SCNN1B and the CRC patients’ prognosis was maintained by multivariate analysis containing tumour stage and lymph node metastasis." (PMID 39415304, 2024). "In summary, we identified for the first time that SCNN1B acts as a tumor suppressor in CRC by targeting of MAPK oncogenic signaling through inactivation of c-Raf, thus impairing MEK-ERK signaling cascades." (PMID 36564468, 2023). "In summary, we identified SCNN1B as a tumor suppressor by functioning as a c-Raf antagonist, which in turn suppressed oncogenic MEK-ERK signaling." (PMID 36564468, 2023). "Taken together, our work has identified SCNN1B as a novel tumor suppressor in CRC via the repression of c-Raf mediated MEK-ERK signaling cascades and is a therapeutic target." (PMID 36564468, 2023). "Using a series of in vitro and in vivo studies, we found that SCNN1B exerted a tumor suppressor function by suppressing cell proliferation by inducing cell cycle arrest and apoptosis." (PMID 36564468, 2023). "The growth of SCNN1B-expressing CRC cell xenografts was largely diminished, thus validating the tumor suppressive function of SCNN1B in vivo." (PMID 36564468, 2023). "A series of in vitro and in vivo studies demonstrated that SCNN1B exerts tumor-suppressive effects in CRC cell lines." (PMID 36564468, 2023). "Apart from SCNN1B protein expression, tumor stage (P < 0.001) was correlated with worse survival by univariate analysis." (PMID 36564468, 2023). "Given that promoter methylation is a prominent factor in silencing of tumor suppressor genes, we next asked if SCNN1B promoter was hypermethylated in CRC." (PMID 36564468, 2023). "At the end point, tumor weight was also significantly suppressed in the SCNN1B-expressing tumors (P < 0.01)." (PMID 36564468, 2023). "The tumor-suppressive effect of SCNN1B is mediated via degradation of GRP78, a chaperone with oncogenic properties." (PMID 31959204, 2020). "We previously identified tumor suppressor genes such as SCNN1B and CAB39L 8, 9 that are silenced by promoter DNA methylation in GC patients." (PMID 31534549, 2019). "The results demonstrated that the methylation status of the SCNN1B promoter was not related to age, sex, tumour differentiation, tumour localization, RAS mutation, BRAF mutation, or MSI status in patients with CRC." (PMID 39415304, 2024).
tumor (continued). "However, the low mRNA levels of SCNN1B had a significant relationship with advanced tumour stage (P = 0.016) and lymph node metastasis (P = 0.014) in CRC patients." (PMID 39415304, 2024). "Collectively, these findings indicate SCNN1B as a functional tumor suppressor in CRC." (PMID 36564468, 2023). "The transcriptional silencing of SCNN1B in CRC, together with its consistent associations with patient survival lend us to hypothesize that SCNN1B may function as a novel tumor suppressor in CRC." (PMID 36564468, 2023). "Besides CRC, SCNN1B was down-regulated in multiple cancer types in TCGA cohort, implying a general tumor suppressive role of this protein." (PMID 36564468, 2023). "Xenograft models validated tumor suppressive function of SCNN1B in vivo." (PMID 36564468, 2023). "Here, we identified SCNN1B as an outlier down-regulated in CRC and it functions as a tumor suppressor." (PMID 36564468, 2023). "The genes with low expression in the tumor group were CRISP3, FAM3D, SCNN1B, CRISP2, RBM20, PHYHIP, C2orf54, SLC5A1, PTCRA, C15orf59, and ANO10." (PMID 35389773, 2022). "The results displayed that the level of SCNN1B and RBPMS2 was significantly reduced while the expression of NFE2L3 and CLDN2 was increased in GC tumor tissues compared to paracarcinoma tissues." (PMID 35137653, 2022). "Similarly, SCNN1B overexpression inhibited the growth of SW1116 xenografts, both in terms of tumor volume (P < 0.05) and tumor weight (P < 0.01) as compared to control tumors." (PMID 36564468, 2023). "After adjustment for potential confounding factors including age, gender, tumor location, and TNM stage, SCNN1B protein expression was found to be an independent prognostic factor for improved survival by multivariate Cox regression analysis [HR: 0.458; 95% C.I.: 0.279–0.753, P = 0.003]." (PMID 36564468, 2023). "Interestingly the proton exchange transporter gene NHE1 (SLC9A1) that is important for tumour metastasis was down-regulated, as well as the sodium channel transporters SCN1A, SCNN1B and SCN7A." (PMID 19662092, 2009). "SCNN1B gene expression is absent in all the CRC cell lines examined, suggesting that SCNN1B might function as a tumor suppressor." (PMID 36564468, 2023). "Although SCNN1B forms a part of the sodium channel ENaC, we found that SCNN1B overexpression had no consistent effect on other ENaC subunits, nor on the sodium content of CRC cells, suggesting that the tumor suppressor function of SCNN1B is independent of its role in ENaC." (PMID 36564468, 2023).
cancer (7 papers, 2020 to 2024). A tumor composed of atypical neoplastic, often pleomorphic cells that invade other tissues. "SCNN1B expression was most closely associated with downregulated genes upon KRAS activation in cancer cell lines (FDR < 0.01)." (PMID 36564468, 2023). "To summarize, cancer-derived intestinal epithelial cells as well as virus-immortalized respiratory epithelial cells expressed an alternative SCNN1B transcript in which intron 3 was partially retained." (PMID 33384439, 2020). "For the eight identified independent prognostic genes, FGFR3 and SCNN1B were downregulated in cancer cells and could function as protective prognostic indicators for CC." (PMID 38672263, 2024). "These are noteworthy that CXCL12 and EPB41L3 were verified by the GEPIA in COAD and READ cancer types while SCNN1B and PYY were documented only in COAD cancer type by the GEPIA." (PMID 35333898, 2022).
bacterial infection (5 papers, 2014 to 2025). "In this review, we will summarize published literature on the Scnn1b-Tg+ mouse and analyze various unanswered questions on the initiation and progression of mucobstruction and bacterial infections." (PMID 31396541, 2019). "Collectively, these data suggest that an amplified adaptive response prevented bacterial infection in DTA+/Scnn1b‐Tg mice." (PMID 29667749, 2018). "To determine whether this underlying inflammation could affect the inflammatory response to bacterial infection, we infected Scnn1b-Tg mice or their WT littermates with PAO1-laden or sterile SCFM2 agar beads." (PMID 40512037, 2025). "Interestingly, macrophage depletion affected various inflammatory characteristics, i.e., alveolar space consolidation, airway inflammation, mucoobstruction, immune cell infiltration, and bacterial infection in Scnn1b-Tg+." (PMID 31396541, 2019). "After PND 10, mucus obstruction becomes more prominent in the main stem bronchi of the Scnn1b-Tg mice, airway inflammation becomes more modest, bacterial infection is intermittent, yet bronchoalveolar lavage (BAL) mucin content and mucin gene transcription remain elevated." (PMID 25204199, 2014).
infection (4 papers, 2018 to 2025). The state of being infected such as from the introduction of a foreign agent such as serum, vaccine, antigenic substance or organism. "Neither the cellular immune responses to infections nor the effects on lung respiratory mechanics have been well characterized in either Scnn1b-Tg mice or SCFM2-C57BL/6J mouse infections." (PMID 40512037, 2025). "Furthermore, there was a significant interaction between the infection with P. aeruginosa and the Scnn1b-Tg genotype on KC/GRO levels, demonstrating a synergistic effect of these parameters on the neutrophil-attractant chemokine." (PMID 40512037, 2025). "Furthermore, Scnn1b-Tg mice were more sensitive to infection and developed higher inflammatory responses to P. aeruginosa infection, making them a compelling model to study chronic bacterial infections." (PMID 40512037, 2025). "Cytokines and chemokines play important roles in responding to infection, in most pwCF and in model infection systems, yet the inflammatory responses to chronic P. aeruginosa infection in Scnn1b-Tg mice are largely unknown." (PMID 40512037, 2025). "Furthermore, as for KC/GRO, there was a significant interaction between the infection with P. aeruginosa and the Scnn1b-Tg genotype on IL-17A levels, demonstrating a synergistic effect of these parameters on the neutrophil-attractant chemokine." (PMID 40512037, 2025). "In scnn1b-transgenic mice, lung inflammation is significantly higher in mice vaccinated with TetR BCG and tetR BCG-vaccinated mice had significantly lower lung MAC CFU post-infection." (PMID 40573950, 2025). "We hypothesize that SCFM2 combined with Scnn1b-Tg mice would promote chronic infection by non-mucoid P. aeruginosa, decrease lung function, and increase innate immune responses to infection relative to WT mice." (PMID 40512037, 2025). "Since Siglec F+ neutrophils, but not total neutrophil counts, were increased in Scnn1b-Tg mice and by the infection, we speculate that this specific neutrophil subset may modulate inflammation during chronic infection with P. aeruginosa." (PMID 40512037, 2025).
respiratory diseases (2 papers, 2021 to 2024). "The results here show significant respiratory diseases associated with likely pathologic variants, such as ABCA3:p.Val1399Met, MUC5B:p.Ile4979Thr, MUC5B:p.Gly5580Arg, MUC5B:p.Glu5621*, SCNN1B:p.Arg206Trp, SCNN1B:p.Glu468Lys, and SFTPA1:p.Gly98Ala." (PMID 33526882, 2021).
gastrointestinal tumors (1 paper, 2023). "Previous studies have explored the role of SCNN1B in gastrointestinal tumors." (PMID 37334354, 2023).
renal disease (1 paper, 2024). "Here, dysfunction in the fns-cb-miR’s targeted gene SCNN1B lead to renal disease in cattle." (PMID 38674383, 2024).